SOX4 (SRY-box transcription factor 4)
Diseases named in the same sentence as SOX4 in open-access papers (continued):
Sharing a sentence is not in itself a finding about the gene and the disease.
tumor (continued). "The association of SOX4 as a central mediator of tumor cell survival and chemoresistance by activation of PI3K/AKT and MAPK signaling has been extensively evaluated in B-cell acute lymphoblastic and myeloid leukemias but this paradigm has not been explored in T-ALL." (PMID 37532715, 2023). "The exosomal miR‐92b‐3p modulated tumor‐associated angiogenesis via targeting SOX4." (PMID 34047469, 2021). "We observed that loss of SOX4 significantly impaired primary tumor growth." (PMID 34584219, 2021). "Furthermore, in line with our previous findings that SOX4 can mediate tumor angiogenesis, these SOX4-deficient tumors were less vascularized than control tumors." (PMID 34584219, 2021). "Consequently, loss of SOX4 leads to a strong impairment of tumor growth in both the mammary fat pad and in the lungs." (PMID 34584219, 2021). "We found Sox4-deficient cells initiate fewer tumours compared with the same number of WT cells." (PMID 27553854, 2016). "Indeed, in many cancers, deregulated expression of Sox4 has been associated with obscured tumor cell growth, survival, apoptosis, invasion or metastasis through the epithelial-to-mesenchymal transition (EMT) mechanism." (PMID 24231253, 2013). "Silencing SOX4 can effectively eliminate the drug resistance caused by lenvatinib treatment and inhibit the proliferation of cancer cells.Conclusions: This study highlights that SOX4 may serve as a promising therapeutic target for tumor treatment." (PMID 37958409, 2023). "Conversely, SOX4 also acts as an oncogene, and TFF3 as a potential tumor suppressor, both linked to OS." (PMID 41646983, 2026). "Analyses of patients with NSCLC has revealed significantly elevated SOX4 expression in tumor tissue, identifying it as an independent prognostic marker." (PMID 41268614, 2026). "miR-133a inhibits cell proliferation, migration and invasion by regulating genes involved in EMT, such as SOX4, and receptors promoting tumor growth, including IGF1R." (PMID 41596525, 2026). "These architectural changes facilitate the upregulation of oncogenic drivers such as SOX4 and GPC3, with SOX4 promoting tumor neovascularization and metastasis, while GPC3 activates Wnt signaling to drive HCC growth." (PMID 40057667, 2025). "Upon the promotion of immune evasion, SOX4 induced expression of MHC class I inhibited protective tumor immunity in triple-negative breast cancer." (PMID 39889187, 2025). "METTL14 inhibits tumor proliferation by promoting the degradation of SOX4 mRNA and has an anticancer effect." (PMID 41446042, 2025). "For instance, a notable study has demonstrated that MMA, which accumulates with age, can induce transcriptional reprogramming by enhancing the expression of the SRY-box transcription factor 4 (SOX4) gene, thereby promoting tumor progression and invasiveness." (PMID 40635714, 2025). "We further validated these findings by analyzing paired HCC and adjacent non-tumor tissues, confirming that SOX4 is predominantly expressed in HCC tissues." (PMID 40399256, 2025). "Current studies of SOX4 molecules in tumours have focused mainly on tumour cells and SOX4 molecules are thought to promote tumour progression by regulating the stemness characteristics of tumour cells." (PMID 40624675, 2025). "SOX4 inhibits the expression of genes in innate and adaptive immune pathways that are critical to protective tumor immunity." (PMID 39889187, 2025). "In conclusion, our in vitro and in vivo studies demonstrate that SOX4 regulates Fatty acid metabolism through ChREBP, thereby inhibiting ferroptosis and promoting angiogenesis and tumor growth in HCC." (PMID 40399256, 2025). "More recently, SOX4 has been recognized as a novel pro-angiogenic regulator, modulate the expression of endothelin-1 (ET-1) and thereby promoting tumor-induced angiogenesis." (PMID 40399256, 2025). "For instance, circDONSON promotes tumor growth and radioresistance through SOX4-mediated Wnt signaling, whereas circRNF10 exhibits tumor-suppressive properties." (PMID 40804731, 2025).
tumor (continued). "And subcutaneous xenograft tumors in nude mice showed that SOX4 knockdown potently inhibited tumor growth, reducing final volume by 60% compared with the control group." (PMID 40399256, 2025). "CSCs showed high expression of stem cell marker genes such as PROM1, ALDH1A1, and SOX4, and increased the activity of tumor-related hypoxia, Wnt/β-catenin, and Notch signaling pathways." (PMID 39107908, 2024). "SOX4 is a marker of poor prognosis that contributes to tumor progression and metastasis formation, with aberrantly high expression in a wide variety of aggressive cancers, and is known to be a master regulator of epithelial mesenchymal transition." (PMID 38172218, 2024). "Immunofluorescence staining of tumor sections indicated a decrease in SOX4 and CD44 expression in tumors of mice treated with IBRD9 compared with untreated tumors." (PMID 37739089, 2024). "Together, these results suggest that the knockdown of SOX4 effectively inhibits tumor growth as well as NE markers expression in vivo." (PMID 39014441, 2024). "Since little is known of the function of SOX genes in NB, we evaluated the expression of SOX11 and SOX4 in a cohort of 395 normal and tumor tissues sequenced in the TARGET dataset." (PMID 38653778, 2024). "Through functional studies in prospectively obtained patient-derived tumoroids, we identify FGF19 as a context-specific target of Wnt in tumor cells with biliary differentiation marked by the embryonic transcription factor SOX4." (PMID 39567523, 2024). "For the in vivo assay, we found that knockdown of SOX4 inhibited tumor growth of subcutaneous xenografts in castrated nude mice which were concomitantly treated with enzalutamide (ENZ)." (PMID 39014441, 2024). "FGF19, downstream of Wnt/β-catenin and SOX4, provides a requisite proliferative signal for surrounding tumor cells and promotes cell cycle progression together with constitutive Wnt activation." (PMID 39567523, 2024). "The expression changes of SOX4 and its relationship with tumor progression were validated in clinical tumor tissues." (PMID 39014441, 2024). "Despite their molecular, genomic, and prognostic differences, we managed to identify SOX4 as a marker of the late tumor clones shared between both Group 3 and Group 4 subgroups." (PMID 39659836, 2024). "By using DESeq221 for our DGE analysis, we discovered that every tumor in both Group 3 and Group 4 datasets showed an upregulation of the SOX4 gene in the later clones, with 10 out of 13 tumors showing a statistically significant upregulation (Padj < .05)." (PMID 39659836, 2024). "The role of somatic SOX4 variation in tumour biology is beyond the scope of this work, but many research studies correlated increased expression of SOX4 with tumorigenesis and progression in several cancer types." (PMID 38397148, 2024). "Our study also identifies SOX4 upregulation as a major event in later tumor clones for Group 3 and Group 4 MBs, suggesting it as a potential therapeutic target for both subgroups." (PMID 39659836, 2024). "There were highly significant correlations between the H Score of P4HB and SOX4 and some clinicopathological parameters of aggressive tumor traits." (PMID 39118797, 2024). "The results showed that SOX4 protein expression was significantly greater in tumor tissues than in adjacent normal tissues." (PMID 38745044, 2024). "We found that in DU-145-shSOX4 or PC-3-shSOX4 cells, the glucose content was increased in the supernatant as compared to the control, reflecting an attenuated intake of glucose in tumor cells after SOX4 knockdown." (PMID 39014441, 2024). "In the SOX4-expressing components of the tumor, a subset of cells with higher nuclear β-catenin levels and cholangiocytic markers express FGF19, which promotes proliferation of surrounding HNF4A-expressing hepatoblastic cells." (PMID 39567523, 2024).
tumor (continued). "To further explore the relationship between SOX4 expression and clinicopathological features of RB development and progression, we performed SOX4 immunostaining in a cohort of 47 RB tumor samples." (PMID 38172218, 2024). "Studies in other cancers show that depending on the type of cancer and cellular context, SOX4 functions as a tumor suppressor, exerting its effects through the induction of apoptosis." (PMID 38653778, 2024). "SOX4, a crucial transcription factor, exhibits high expression in various cancers and plays a significant role in controlling tumor cell proliferation, invasion, and metastasis." (PMID 39349443, 2024). "Then, we studied the role of SOX4-induced BMI1 expression in tumor proliferation and metastasis by establishing subcutaneous and orthotopic models in mice." (PMID 39349443, 2024). "To evaluate the effect of SOX4 on tumor growth in vivo, we established a xenograft mouse model in castrated nude mice by inoculating DU-145 or PC-3 shSOX4 cells." (PMID 39014441, 2024). "In order to explore the relationship between SOX4 and lncrna and miRNA we, therefore, analyzed the ceRNA regulatory network of SOX4 in tumor tissues of LIHC." (PMID 37958409, 2023). "For the prognostic model based on the SOX4-associated energy-metabolism-related genes, 100 genes were collected and their correlations with SOX4 expression across various tumor types were visualized using cluster heatmaps." (PMID 37958409, 2023). "In gastric cancer, RBBP4 is recruited as part of the NuRF complex by the circular RNA circ-DONSON to promote SOX4 expression and produce tumor-promoting effects." (PMID 38028543, 2023). "SOX4 in mammalian cells has been shown in both normal and tumor cells to maintain an undifferentiated state that is associated with stemness." (PMID 37021774, 2023). "For the prognostic model based on the SOX4-associated EMT-related genes, 95 genes were collected and their correlations with SOX4 expression across various tumor types were visualized using cluster heatmaps." (PMID 37958409, 2023). "Overexpression of LINC00470 or SOX4 partially abolished the suppressive effect of temozolomide and conspicuously elevated tumor volume and weight in nude mice in the presence of temozolomide." (PMID 36987665, 2023). "For example, STAT3 participates in the regulation of SOX4 to promote tumor progression in hepatic cell carcinoma." (PMID 37298609, 2023). "The present study aimed to visualize the expression, survival, mutations, methylation, ceRNA network, immunity, and prognostic models, as well as explore the potential role, of SOX4 across different tumor types and specific LIHC using different online tools." (PMID 37958409, 2023). "Although emerging research has evaluated the expression level and function of SOX4 in certain tumors, its roles across various tumor types, especially aspects related to prognostic potential and clinical significance, have not been systematically studied." (PMID 37958409, 2023). "In the present study, we firstly elucidated SOX4 expression and explored its correlation with prognosis in human tumor tissues." (PMID 37958409, 2023). "This study aims to visualize the expression, survival, mutation, methylation, ceRNA network, and immune and prognostic models, as well as to explore the potential role of SOX4 in different tumor types and specific LIHCs using different online tools." (PMID 37958409, 2023). "The study also showed that SNHG17 can act as an endogenous “sponge” by competing with miR-338-3p to regulate SOX4, consequently promoting tumor progression." (PMID 38090151, 2023). "TM4SF1+, SOX4+, and MKI67+ tumor cells; CXCL12+ cancer-associated fibroblasts; CD4+ resident memory T cells; Treg; IgA+ plasma cells; and several myeloid subsets were enriched in stage IV CRC, most of which were associated with overall survival of patients." (PMID 37360193, 2023).
tumor (continued). "In this study, a comprehensive analysis and experimental validation were performed to explore the function of SOX4 across tumor types." (PMID 37958409, 2023). "Especially in LIHC, the result shows that SOX4 expression was significantly correlated with tumor purity in TIMER." (PMID 37958409, 2023). "Considering the limited availability of normal data in the TCGA database, we integrated the TCGA and GTEx data to study the difference in SOX4 mRNA expression in nine tumor types." (PMID 37958409, 2023). "Mechanistic studies revealed that zotatifin reprograms the tumor translational landscape, inhibits the translation of Sox4 and Fgfr1, and induces an interferon (IFN) response uniformly across models." (PMID 37874652, 2023). "First, we performed immunoblotting on a biological replicate of 2153L tumor samples and observed a dramatic reduction in Sox4 and Fgfr1 protein expression in the zotatifin treatment group." (PMID 37874652, 2023). "The effects of temozolomide via the LINC00470/EGR2/SOX4 axis on tumor growth as well as apoptosis and autophagy were also evidenced in nude mice." (PMID 36987665, 2023). "High IL-6 and Sox4 expression was closely related to tumor size, TNM stage, and a poorer overall survival." (PMID 35513871, 2022). "IHC assay also indicated that hsa_circ_0000277 induced inhibitory effects on SOX4, β-catenin, c-myc and cyclin D1 protein levels in tumor tissues." (PMID 35241028, 2022). "To further elucidate this assumption, we analyzed the protein expression of YAP, BMI1, and SOX4 (stemness-related genes) in tumor tissue." (PMID 35322024, 2022). "Meanwhile, we discovered that high expression of Sox4 was relevant to large tumor size (p = 0.0039) and TNM stage (p = 0.0034) in 108 cases of OSCC patients." (PMID 35513871, 2022). "As reported in a recent study, MMA is sufficient to stimulate the progression and aggressiveness of the tumor by inducing SOX4 by activating autocrine TGFβ signaling." (PMID 35656023, 2022). "The authors measured a significant decrease in tumor growth and a reduced expression of SOX4, Wnt1, and β-catenin in tumor tissues." (PMID 35955703, 2022). "Survival analyses revealed that patients with low SOX4 expression had significantly higher tumor-free survival and disease-specific survival than those with high SOX4 expression." (PMID 36193492, 2022). "Subsequently, we found that the tumours expressed SOX4 at much higher levels when compared with the adjacent normal tissue." (PMID 35522942, 2022). "In previous research, we have introduced that the integrin αvβ6–TGFβ–SOX4 pathway promotes immune evasion and tumor progression in TNBC." (PMID 35267473, 2022). "In HCC, the SOX4 expression is remarkably increased in tumor tissues, especially in metastatic and recurrent HCC samples." (PMID 35267473, 2022). "Next, we analyzed SOX4 expression in the Wurmbach and Mas liver datasets and found markedly elevated SOX4 mRNA levels in tumor tissue in relative to normal tissue (P = 0.003, <0.001, respectively)." (PMID 33995626, 2021). "Future work should be aimed at developing methodologies to interfere with SOX4-functionality, thereby stimulating differentiation of tumor cells to a post-mitotic state." (PMID 34584219, 2021). "In accordance, knockdown of SOX4 leads to impaired metastasis formation and in some studies, reduced primary tumor growth." (PMID 34584219, 2021). "SOX4, a sox transcription factor, has been demonstrated to play an oncogenic role and was related to tumor progression and development." (PMID 34258391, 2021). "To further confirm the stimulatory effect of SOX4 on the stemness of CRC cells, we examine the frequency of sphere-forming and tumor-initiating cells of SOX4-overexpressing cells and their control cells by LDA assay." (PMID 33482915, 2021). "Taken together these data suggest that SOX4 affects tumor growth by maintaining a stem/progenitor gene program which regulates proliferative capacity in a cell-autonomous manner." (PMID 34584219, 2021).
tumor (continued). "SOX4 expression was upregulated in tumor tissues (n = 36) and cells compared with that in normal tissues (n = 36) and cells." (PMID 34258391, 2021). "As demonstrated by qRT-PCR, depletion of THAP9-AS1 resulted in a decline of THAP-AS1 and SOX4 mRNA expression, while an increase of miR-133b in excised tumor tissues." (PMID 33854048, 2021). "The abnormal expression of SOX4 is significantly related to tumor characteristics and prognosis of patients." (PMID 34496348, 2021). "The ROC analysis of SOX4 in the GSE14520 dataset, HBV-related HCC cohort indicated that SOX4 had a high accuracy of distinguishing tumor tissues from adjacent non-tumor liver tissues (P <0.001, AUC of the ROC curves = 0.782)." (PMID 33995626, 2021). "The lack of growth of SOX4KO tumors and the single cell RNA-sequencing data suggest that SOX4 regulates cycling of tumor cells." (PMID 34584219, 2021). "These processes are all essential for cycling of (tumor) cells and this indicates that SOX4 is essential to keeping the cells in a state that is primed to maintain active cycling." (PMID 34584219, 2021). "Correlations between β-catenin, SOX-4 and invasion area and histological grading of tumor tissue which has grown through the prostate." (PMID 34157052, 2021). "To further assess the function of SNHG17 in tumorigenesis and tumor progression, we analyzed a downstream target of miR-338-3p, SOX4, and predicted two binding sites within the 3′UTR of SOX4." (PMID 34429400, 2021). "Mechanistic analysis suggested that SNHG17 acts as an endogenous “sponge” competing with miR-338-3p to regulate SOX4, thereby promoting tumor progression." (PMID 34429400, 2021). "Nevertheless, in some tumors, like melanoma or bladder cancer SOX-4 can behave as a tumor suppressor, promoting cell cycle arrest and apoptosis." (PMID 34157052, 2021). "We also performed IHC staining of other top-ranked TFs including SIX1, RUNX1, and SOX4 and again found higher expression level of these TFs in tumor tissues." (PMID 34001209, 2021). "In different types of tumors or different stages of tumors, SOX4 plays a dual role by participating in the process of tumor cell proliferation, apoptosis or differentiation: tumor promotion and tumor inhibition." (PMID 34496348, 2021). "Restoring miR-335 content downregulates SOX4, modifying the tumor microenvironment and markedly reducing tumor formation." (PMID 34945712, 2021). "First, in a model of SOX4 upregulation via TGFβ-1, since this cytokine is produced in higher levels in MM, by both tumor cells and BMSCs, exerts inhibitory effects on normal B-cell proliferation and Ig secretion, and regulates the secretion IL-6 in MM cells." (PMID 34945712, 2021). "SCAMP3 level was positively correlated with disease stages and tumor grades and negatively correlated with patient survival; SOX4, STK39, TARBP1, and TDRKH can be regarded as potential prognosticators and therapeutic targets for HCC." (PMID 34277395, 2021). "Further, we detected the expression of SOX4 in clinical GC tumor tissue and normal tissues, the increased level of SOX4 was found in tumor tissues." (PMID 34496348, 2021). "SOX4 has been suggested to promote tumor angiogenesis through CXCR4 and endothelin-1 in breast and hepatocellular tumors, respectively, in 2 recent studies." (PMID 34228647, 2021). "MiR-133a plays the tumor suppressive role via tageting and regulating the genes like SOX4, EGFR, FSCN1, COL1A1 and so on." (PMID 33391416, 2021). "Taken together, these results suggest that lnc-42060, as a sponge of miR-204-5p, regulates SOX4 expression and activity, thereby further inhibiting tumor progression and sensitizing cells to TAM." (PMID 34235197, 2021). "Overexpression of SOX4 mRNA and protein in pancreatic tissues compared with non-tumor tissues was observed in RT-qPCR and western blot assays." (PMID 33824274, 2021). "The SOX4 gene modulates tumor development and growth, epithelial-mesenchymal transition and metastasis 14, 32-34." (PMID 33995626, 2021).